SMO (smoothened, frizzled class receptor)
Diseases named in the same sentence as SMO in open-access papers (continued):
Sharing a sentence is not in itself a finding about the gene and the disease.
odontogenic tumors (4 papers, 2020 to 2025). "Recent studies have provided robust evidence that the activation of the MAPK signaling pathway plays a significant role in the pathogenesis of this odontogenic tumor, with SMO and BRAF V600E mutations being the most observed." (PMID 38615253, 2024). "Furthermore, the potential of SMO and PTCH1 mutations to guide the treatment of selected odontogenic tumours warrants further investigation." (PMID 41364259, 2025). "Immunoreactivity for SHH, PTC, SMO, and GLI-1 was detected in both epithelial-derived odontogenic tumors and epithelial-mesenchymal-derived odontogenic tumors with or without dental hard tissue formation." (PMID 33374329, 2020).
skull base meningioma (4 papers, 2020 to 2025). A meningioma that arises from the skull base. "Concerning the three NF2-wild type IVMs, none had mutations in AKT1, PIK3CA or SMO genes, which are typically altered in skull base meningiomas." (PMID 35049691, 2022). "In cases of NF2-mutant skull base meningiomas refractory to surgery and radiation, currently, there is no effective chemotherapy; however, PIK3CA, SMO and AKT1 represent promising future therapeutic targets." (PMID 40075786, 2025).
Stroke (4 papers, 2014 to 2025). Sudden impairment of blood flow to a part of the brain due to occlusion or rupture of an artery to the brain. "The treatment with BHD increased the levels of Shh, SMO, Ptch1 and Gli1 in the right hippocampus and cortex after stroke." (PMID 40973940, 2025). "In particular, small molecules targeting SMO have recently been explored in cancer (i.e., SMO antagonists), stroke, and demyelinating disorders (i.e. SMO agonists)." (PMID 34135312, 2021). "Reactive astrocytes of the glial scar expressed Shh, Ptch1 and SMO at 14 d after stroke." (PMID 25341035, 2014).
triple-negative breast carcinoma (4 papers, 2018 to 2023). An invasive breast carcinoma which is negative for expression of estrogen receptor (ER), progesterone receptor (PR), and human epidermal growth factor receptor 2 (HER2). "The EDALINE Study investigates targeting the Hedgehog pathway via combined SMO inhibition and docetaxel therapy in patients with advanced triple-negative breast cancer." (PMID 33006013, 2020). "Inhibition of this pathway with SMO-inhibitors, vismodegib and sonidegib, made triple-negative breast cancer mouse model cells more sensitive to docetaxel." (PMID 33006013, 2020). "Although, numerous SMO inhibitors like GDC-0449 (Vismodegib) have entered clinical trials for triple negative breast cancer patients but their efficacy still remains uncertain." (PMID 29329585, 2018). "Moreover, the noncanonical route of GLI activation has been frequently reported in many other solid tumors, such as NSCLC, PDAC, gastric adenocarcinomas, and triple-negative breast cancer, leading to SMO inhibitor resistance." (PMID 34572373, 2021). "Moreover, smoothened homolog (SMO) and GLI1 were highly expressed in triple negative breast cancer, and their increased expression was correlated with metastasis, poor prognosis, and recurrence of triple negative breast cancer." (PMID 36701089, 2023).
chondrosarcoma (3 papers, 2018 to 2023). A malignant cartilaginous matrix-producing mesenchymal neoplasm arising from the bone and soft tissue. "In chondrosarcoma, pre-clinical findings demonstrated that SMO inhibitors significantly decreased tumor size and cellularity in human chondrosarcoma xenograft." (PMID 31035664, 2019). "Then, Using qRT-PCR, we measured the expression of IHH, PTCH1, SMO, and GLI1 and found that their levels were significantly lower in normal articular cartilage compared to any other chondrosarcomas, particularly in dedifferentiated chondrosarcoma." (PMID 37488121, 2023). "Expression of PTCH1, SMO, and GLI1 proteins was detected in chondrosarcoma patient tissues and three chondrosarcoma cell lines (HC-a, SW1353, and JJ012), but not in normal articular cartilage tissues." (PMID 30081498, 2018). "Of note, data from this study indicated that activation of Hh signaling in chondrosarcoma cancer cells is type I noncanonical Hh signaling (GLI1-dependent and SMO-independent) since the Hh pathway activity can be diminished by GLI1 knockdown, but not by cyclopamine treatment." (PMID 30081498, 2018).
Ewing sarcoma (3 papers, 2016 to 2021). A small round cell tumor that lacks morphologic, immunohistochemical, and electron microscopic evidence of neuroectodermal differentiation. "To corroborate that CSNK1D inhibition is a potent strategy to block GLI activation in SMOi-resistant settings, we performed chemical inhibition of CSNK1D in A673 and MHH-ES-1 Ewing sarcoma cells both showing SMO-independent GLI1 expression." (PMID 34439381, 2021). "To expand our investigations towards SMOi-resistant cancer cells, we turned to Ewing sarcoma (EWS) cells, where SMO-independent GLI1 expression is driven by the EWS–FLI1 fusion oncogene." (PMID 34439381, 2021).
lung adenocarcinoma (3 papers, 2017 to 2026). A carcinoma that arises from the lung and is characterized by the presence of malignant glandular epithelial cells. "Alterations of the SMO gene (mutation, amplification, mRNA overexpression) were found in 12.2% of tumors of The Cancer Genome Atlas (TCGA) lung adenocarcinomas by whole-exome sequencing." (PMID 28416737, 2017).
malignant pleural mesothelioma (3 papers, 2013 to 2021). A malignant neoplasm that arises from mesothelial cells in the pleura and shows a diffuse growth pattern. "A hampered Survivin expression following SMO inhibition has further been described for malignant pleural mesothelioma, an effect rescued by overexpression of GLI1, suggesting an involvement of GLI1 transcription factor." (PMID 30142876, 2018).
metastatic disease (3 papers, 2016 to 2021). "Although this patient’s cutaneous BCCs responded to SMO inhibitors, his metastatic disease progressed and developed new nodules." (PMID 34639065, 2021). "In addition, the SMO inhibitor-docetaxel combined treatment was effective in treating a proportion of women with metastatic disease who had previously failed on taxane chemotherapy." (PMID 34381714, 2021).
myeloid leukemia (3 papers, 2013 to 2019). A clonal proliferation of myeloid cells and their precursors in the bone marrow, peripheral blood, and spleen. "The expression of Hh signaling proteins, including SMO and GLI1 in radiation-resistance myeloid leukemia cells, are higher than that observed in radiation-sensitive myeloid leukemia cells, suggesting that Hh pathway activation is related to radiotherapy resistance." (PMID 30987263, 2019).
ovarian tumors (3 papers, 2011 to 2023). "In addition, we analyzed SHH, SMO, Ptch1, and Gli1 mRNA levels in the 4 individual patient samples we used to generate tumor xenografts for analyzing the effect of Hh pathway inhibition on ovarian tumor growth in vivo." (PMID 22140510, 2011). "Consistent with previous results, GLI1 and GLI3 (HH pathway transcriptional effectors), PTCH1 (HH signaling repressor and target gene), SMO (HH signaling activator), IHH and SHH (HH pathway ligands) were expressed in ovarian tumors, albeit at variable levels." (PMID 26755648, 2016).
renal cell carcinoma (3 papers, 2020 to 2024). "In contrast, mRNA analysis of the elements of the Hedgehog signaling pathway, such as SHH, SMO, and GLI1 in tissue from renal cell carcinoma showed higher expression levels than healthy tissue, while an underexpression of PTCH1 was observed and specifically in patients older than 60 years." (PMID 38287479, 2024). "However, a limitation of our study is that we just checked the different expression levels of SHH, PTCH and SMO in different tumour gradings, and then we used analysis data from the GDC TCGA renal cell carcinoma (282 patients) to draw the survival curve." (PMID 37240278, 2023).
skin tumors (3 papers, 2019 to 2022). "Real-time PCR analysis demonstrated that BCC showed remarkably enhanced mRNA expression of all HH molecules, except SMO compared to other skin tumors." (PMID 31756206, 2019). "As expected, out of the nine skin tumors examined, only BCCs exhibited substantially elevated levels of all the HH-related molecules, except SMO." (PMID 31756206, 2019). "Real-time PCR results demonstrated that all HH-related molecules, except SMO, were remarkably elevated in BCC compared to normal skin and most other skin tumors." (PMID 31756206, 2019). "Hedgehog/GLI (HH/GLI) signaling inhibitors targeting the central pathway transducer Smoothened (SMO) have shown to be clinical efficacious in skin cancer; however, several mechanisms of non-canonical HH/GLI pathway activation limit their efficacy." (PMID 33958721, 2021).
acute leukemia (2 papers, 2017 to 2023). A clonal (malignant) hematopoietic disorder with an acute onset, affecting the bone marrow and the peripheral blood. "Additionally, Smoothened (SMO) inhibitors, such as Glasdegib, control the progression of acute leukemia by specifically targeting the Hedgehog (Hh) signaling pathway." (PMID 38007419, 2023).
Angiomatous Meningioma (2 papers, 2014 to 2025). A WHO grade I meningioma characterized by the presence of small and medium sized vessels that predominate over the meningioma cells. "Mutations in AKT1, KLF4, POLR2A or SMO were mostly detected in meningothelial or transitional meningioma, except for three cases: one case of angiomatous meningioma with KLF4 mutation, one case of secretory meningioma with KLF4 mutation and one case of psammomatous meningioma with AKT1 mutation." (PMID 40815185, 2025).
Anxiety (2 papers, 2024). Intense feelings of nervousness, tension, or panic often arise in response to interpersonal stresses. "In contrast to PTCH +/− mice, SMO-deficient mice, in which SHH signaling is suppressed, exhibit increased anxiety/depression-like behaviors without affecting spatial and fear-related learning ability." (PMID 39290714, 2024).
asthma (2 papers, 2020 to 2022). "The activation of SMO activity in bronchial epithelia enhanced the allergen-induced goblet cell metaplasia, which is defined as a reversible transformation of airway epithelial cells to mucous cells such as goblet cells and may occur in asthma." (PMID 33303027, 2020). "Collectively, our primary cell data showed an upregulation of SHH, SMO, GLI2 and PTCH1 gene expression with epithelial differentiation independent of a diagnosis of asthma." (PMID 36230980, 2022).
cervical cancer (2 papers, 2022). A primary or metastatic malignant neoplasm involving the cervix. "The mRNA expression of key proteins such as PTCH1, SMO, and GLI1 was downregulated significantly, indicating that CAR may prevent cervical cancer by modulating hedgehog signaling powerfully." (PMID 36712982, 2022). "Moreover, CAR inhibited the HH/GLI signaling pathway by down regulating the expression of SMO, PTCH and GLI1 proteins in cervical carcinoma cells." (PMID 36712982, 2022).
chordoma (2 papers, 2019 to 2024). Chordomas are rare malignant tumors arising from embryonic remnants of the notochord in axial skeleton. "Conversely, vismodegib (GDC-0449), another SMO inhibitor, has shown mixed results, inhibiting chordoma growth but potentially enhancing tumour proliferation in certain contexts." (PMID 39568072, 2024). "Chemotherapy with HH inhibitors - in the sense of Shh, GLI- and SMO-inhibitors - could represent a therapeutic approach in many chordoma patients with multiple relapses." (PMID 30769952, 2019). "Our results suggest that Hedgehog-inhibitors, like SHH-, GLI- and SMO- inhibitors, might serve as a potential and effective target for the treatment of chordomas." (PMID 30769952, 2019).
ciliopathies (2 papers, 2018 to 2025). "Our findings suggest that RHOA activation downstream of SMO might be unaffected in cells with abnormal cilia, as a consequence of ciliopathies or oncogenic transformation, since many cancer cells lack primary cilia." (PMID 30148884, 2018). "In summary, our findings demonstrate that non-canonical Hh signaling mediated by events proximal to PTCH1 and SMO occur independently of primary cilia and, therefore, might be of relevance in cancer and ciliopathies." (PMID 30148884, 2018).
colorectal tumor (2 papers, 2009 to 2021). "Furthermore, we found that DNA methylation of SMO, a component of Hedgehog (Hh) signaling, was tightly linked to colorectal tumors with BRAFV600E." (PMID 20027224, 2009). "Functionally, treatment with vismodegib has been shown to increase the number and size of colorectal tumors in mice in colitis-associated models, while the experimental Hh agonist, SAG21k, which acts at the level of SMO, decreased the colorectal tumor burden." (PMID 33498528, 2021). "Our data indicates that CIMP-specific promoter DNA hypermethylation might be involved in the repression of SMO in colorectal tumors carrying BRAFV600E." (PMID 20027224, 2009). "Furthermore, we also found that DNA methylation of SMO and HHIP were closely linked to colorectal tumors with BRAFV600E." (PMID 20027224, 2009).
cyst (2 papers, 2022 to 2025). A sac-like closed membranous structure that may be empty or contain fluid or amorphous material. "The Pck ARPKD rat model also shows elevated SMO and GLI proteins in the lining of the cyst epithelium and responded to treatment with the SMO inhibitor, cyclopamine, leading to reduced renal cyst area." (PMID 39823139, 2025). "Analysis of SMO revealed high immunohistochemical expression in all OKC cases, with the observation of brown staining in cells of all layers of the epithelial lining of this cyst, except for the superficial parakeratin layer." (PMID 36287504, 2022). "However, in the case of OKCs, it is believed that the sum of this cytoplasmic SMO/GLI-1 correlation along with the strong cytoplasmic and nuclear expression of GLI-1 may contribute to the high growth potential of this cyst." (PMID 36287504, 2022).
head and neck squamous cell carcinoma (2 papers, 2020 to 2024). A squamous cell carcinoma that arises from any of the following anatomic sites: lip and oral cavity, nasal cavity, paranasal sinuses, pharynx, larynx, and salivary glands. "In head and neck squamous cell carcinoma (HNSCC) cells, H3K4ac modulated by HDAC3 is enriched around the transcription start site of EMT related genes such like GLI1 and SMO, co-overexpression of which promotes HNSCC cell invasion and migration ability." (PMID 33262941, 2020).
holoprosencephaly (2 papers, 2021 to 2022). Holoprosencephaly (HPE) is a complex brain malformation resulting from incomplete cleavage of the prosencephalon, occurring between the 18th and 28th day of gestation, and affecting both the forebrain and face, which results in neurological manifestations and facial anomalies of variable severity. "Numerous PTCH1 mutations associated with the human birth defect holoprosencephaly increase its ability to inhibit SMO." (PMID 35757007, 2022). "The holoprosencephaly is thought to be secondary to reduced HH signaling caused by the accumulation of SMO-inhibiting sterols." (PMID 35757007, 2022). "The blockade of SHH by cyclopamine (an antagonist that binds SMO) also causes holoprosencephaly, which is evidence that SHH signalling is also involved." (PMID 34576017, 2021). "In contrast, the complete absence of SMO or SHH in mouse models resulted in holoprosencephaly because SHH is required for cell migration and axonal guidance in the developing brain." (PMID 34576017, 2021).
Keratocystic odontogenic tumor (2 papers, 2014 to 2022). An intraosseous odontogenic neoplasm that usually arises from the mandible. "To assess potential DNA alterations related to keratocystic odontogenic tumors (KCOTs), we sequenced smoothened (SMO) genes in 12 sporadic KCOTs." (PMID 25189937, 2014).
leiomyosarcoma (2 papers, 2020 to 2021). An uncommon, aggressive malignant smooth muscle neoplasm, usually occurring in post-menopausal women. "Recently, we demonstrated that uterine leiomyosarcoma cells exhibited an upregulation of SMO and GLI1 members concomitantly with an increase in nuclear translocation of GLI-1 and 2 compared to uterine smooth muscle cells." (PMID 33179013, 2020). "Inhibition of DNA methyltransferase by 5aza-dC was found to reduce PTCH1 DNA methylation, accompanied by decreased SMO and GLI1 expression and inhibition of GLI1 and GLI2 nuclear translocation in leiomyosarcoma cell lines." (PMID 34572373, 2021). "Elevated expression of SMO and GLI 1 was observed in leiomyosarcoma when compared to normal myometrium and uterine fibroids tissue." (PMID 33179013, 2020).
lung fibrosis (2 papers, 2013). "For instance, TGF-ß, a growth factor that plays a critical role in lung fibrosis and in cancer development, interacts with Hh pathway downstream of SMO, increasing the expression of Gli2 in mice and in cancer cells." (PMID 23667589, 2013). "Similarly, in Idiopathic pulmonary fibrosis, Shh ligand is expressed in bronchiolar and alveolar epithelial cells while Ptch1 and SMO have been observed in fibroblasts and mesenchymal cells forming fibroblast foci." (PMID 23667589, 2013).
malignant mesothelioma (2 papers, 2018 to 2023). A malignant neoplasm of the pleura or peritoneum, arising from mesothelial cells. "Timer database analysis revealed that immune cell infiltration mechanisms in malignant mesothelioma were closely associated with SMO and GLI1 expression." (PMID 37139482, 2023). "Malignant mesotheliomas can have mutations in PTCH1, Smoothened (SMO), and SUFU genes." (PMID 29498494, 2018). "In conclusion, this study analyzed the relationship between SMO and GLI1 expression prognosis and immune cell infiltration mechanisms in malignant mesothelioma tissues by immunohistochemistry, RT-qPCR, and bioinformatics." (PMID 37139482, 2023).
Meningothelial Meningioma (2 papers, 2021). A WHO grade I meningioma characterized by the presence of tumor cells that form lobules. "The proportion of meningothelial meningiomas harboring AKT1, KLF4, SMO, or POLR2A mutations was significantly high." (PMID 33772057, 2021).
neuroblastoma (2 papers, 2012 to 2021). Neuroblastoma (NB) is the most common solid, extracranial childhood tumor. "We identified six genes (DLGAP5, DSCC1, SMO, SNRPD1, SSBP1, and UBE2C) with a vital role in mitosis and these are promising therapeutic targets for neuroblastoma." (PMID 23251412, 2012).
osteoporosis (2 papers, 2025). A condition of reduced bone mass, with decreased cortical thickness and a decrease in the number and size of the trabeculae of cancellous bone (but normal chemical composition), resulting in increased fracture incidence. "Blocking the Hh pathway through the specific deletion of Ptch1 in HOC+ mature osteoblasts leads to severe osteoporosis, and the deletion of SMO in Osx+ or Gli1+ osteogenic progenitors also results in decreased bone formation." (PMID 40141354, 2025).
prostate adenocarcinoma (2 papers, 2022 to 2025). "Specifically in PCa, loss of SMO, a key canonical transducer of Hh signaling, was demonstrated as a molecular event occurring during transition from prostate adenocarcinoma into NEPC." (PMID 39748059, 2025).
retinoblastoma (2 papers, 2021 to 2026). A malignant tumor that originates in the nuclear layer of the retina. "Also, SHH and WNT pathways were significantly enriched in IO-MEPLs compared to retinoblastomas with increased expression levels of CTNNB1 and SMO." (PMID 34785636, 2021).
adenoma (1 paper, 2022). A neoplasm arising from the epithelium. "SMO is deubiquitinated by USP8 and this modification alters its target region, possibly linking this mutation to the already described mechanisms of USP8-mutated adenomas." (PMID 35743266, 2022). "Finally, USP8 has been shown to increase Sonic Hedgehog (SHH) signaling by promoting SMO activity, even if the possible implications of this alteration have not been studied in USP8-mutated corticotrope adenoma cells to date." (PMID 35743266, 2022).